FSTL1 (follistatin like 1)
Diseases named in the same sentence as FSTL1 in open-access papers (continued):
Sharing a sentence is not in itself a finding about the gene and the disease.
adenoma (1 paper, 2018). A neoplasm arising from the epithelium. "A diffuse and intense staining of FSTL1-positive cells was also seen in the lamina propria compartment of adenoma and CRC sections." (PMID 30131854, 2018). "Moreover, immunostaining of normal and tumoral colonic sections showed a more pronounced expression of FSTL1 in adenoma and CRC cells as compared to normal colonic epithelial cells." (PMID 30131854, 2018).
aortic stenosis (1 paper, 2025). Aortic valve stenosis is a aortic valve disease caused by the incomplete opening of the aortic valve. "While FSTL1 undoubtedly influences various aspects of cardiovascular health, its overall impact on the development of aortic stenosis remains to be fully elucidated." (PMID 40076529, 2025). "Given its critical role in valvular development, it is unsurprising that FSTL1 has emerged as a potential biomarker in patients with aortic stenosis." (PMID 40076529, 2025). "Taken together, these findings highlight the complex and potentially paradoxical role of FSTL1 in aortic stenosis, with both pro-inflammatory and protective effects." (PMID 40076529, 2025).
aortic valve calcification (1 paper, 2022). "Nevertheless, there is little information regarding the exact role of FSTL1 in aortic valve calcification." (PMID 36684598, 2022). "This study aimed to determine whether follistatin-like 1 (FSTL1) is associated with calcific AS events and its exact role in aortic valve calcification." (PMID 36684598, 2022).
arterial disease (1 paper, 2021). "It would be interesting to examine whether those secreted proteins (Bgn,Cpe,Emillin1,Fstl1,Nid1,Mgp,Sparc, and Spp1) validated by our ISH are the result of the arterial disease or play a direct causative role." (PMID 34762601, 2021).
atherosclerosis (1 paper, 2025). A disease characterized by the build-up of fatty material and calcium deposition in the arterial wall resulting in partial or complete occlusion of the arterial lumen. "The relationship between FSTL1 and heart disease may be context-dependent, with FSTL1 levels increasing primarily in response to metabolic disturbances and inflammation rather than reflecting the extent of atherosclerosis in stable patients." (PMID 41187309, 2025).
atrioventricular valve anomalies (1 paper, 2019). "We conclude that pathogenic variants in FSTL1 are unlikely to be responsible for skeletal or atrioventricular valve anomalies in humans." (PMID 30722102, 2019).
bladder cancer (1 paper, 2022). "Subsequently, in vitro validation of the FSTL1 gene and protein expression demonstrated that FSTL1 expression was downregulated in bladder cancer cells compared to that in the normal SV-HUC-1 cell line." (PMID 35450397, 2022). "We also found that the combination of FSTL1, stage, age, and gender achieved an AUC value of 0.76 in predicting bladder cancer recurrence." (PMID 35450397, 2022). "A total of 15 paired BLCA and normal tissue specimens, human immortalized uroepithelial cell lines, and bladder cancer cell lines were selected for the validation of the difference in expression of FSTL1 between normal tissues and BLCA." (PMID 35450397, 2022). "In this study, we identified six ECM-related genes (CTHRC1, MMP11, COL10A1, FSTL1, SULF1, and COL5A3) that were associated with bladder cancer occurrence, tumor stage, and prognosis based on the bladder cancer tumor samples." (PMID 35450397, 2022). "The FSTL1 protein level was lower in bladder cancer than that in the normal bladder samples." (PMID 35450397, 2022). "In contrast, the expression quantity of FSTL1 in the bladder cancer tissues was lower than that in the normal bladder tissues." (PMID 35450397, 2022). "FSTL1 was found to be correlated with a negative prognosis for bladder cancer." (PMID 35450397, 2022).
brain ischemia (1 paper, 2023). Diminished or absent blood supply to the brain caused by obstruction (thrombosis or embolism) of an artery resulting in neurologic damage. "The role and mechanism of circHECTD1 in OGD/R-induced cell damage have been investigated by detecting levels of CircHECTD1, miR-27a-3p, and Follistatin-like 1 (FSTL1) by quantitative real-time polymerase chain reaction (RT-qPCR) in a model of brain ischemia." (PMID 36830585, 2023).
breast invasive carcinoma (1 paper, 2023). "Although patients with breast invasive carcinoma (BRCA) from the TCGA database with high and low/medium FSTL1 expression had the same survival rate before 4000 days, they seemed to have a better survival rate over a more extended period." (PMID 37238210, 2023). "All individual stages of invasive breast cancer lacked FSTL1 expression compared with normal breast tissues." (PMID 37238210, 2023).
campomelic dysplasia (1 paper, 2019). "The phenotype of Fstl1 KO mice is comparable to a rare genetic disorder known as Campomelic Dysplasia (CD; OMIM 114290) (Mansour, Hall, Pembrey, & Young, 1995)." (PMID 30722102, 2019). "Based on the phenotype of the Fstl1 KO mice, we selected 15 patients with unexplained skeletal dysplasia, of which 12 have campomelic dysplasia, 2 have small patella syndrome, and 1 with BILU." (PMID 30722102, 2019). "To this end, we selected 69 patients with genetically unresolved campomelic dysplasia, small patella syndrome, BILU syndrome, kyphoscoliosis and/or defects of the mitral or tricuspid valves, and Sanger sequenced the FSTL1 gene body and determined the copy number." (PMID 30722102, 2019).
chronic lung disease (1 paper, 2016). According to the definitions of the American and British Thoracic Societies, including pulmonary functional tests, X-rays, and CT scans for items such as fibrosis, bronchiectasis, bullae, emphysema, nodular or lymphomatous abnormalities. "In the case of FSTL1 and BMP4 receptors, FSTL1 may be able to act onto BMP4 receptors when epithelial cells are immature in the early stage of lung development or injured during chronic lung diseases." (PMID 27355685, 2016).
clear-cell renal cell carcinoma (1 paper, 2018). "We previously showed that the expression of follistatin-like protein 1 (FSTL1) was significantly down-regulated in metastatic clear-cell renal cell carcinoma (ccRCC)." (PMID 29357946, 2018).
colitis (1 paper, 2023). Inflammation of the colon. "The pro-inflammatory cytokine follistatin-like protein 1 (FSTL1) is a member of the FST class that is upregulated in active colitis of human and mice." (PMID 37391444, 2023). "Importantly, FSTL1 greatly enhances the production of other inflammatory cytokines through facilitating M1 pro-inflammatory polarization and inhibiting M2 anti-inflammatory polarization of macrophages; these activities then serve to aggravate DSS-induced colitis." (PMID 37391444, 2023).
colon adenoma (1 paper, 2018). An adenoma that arises from the colon. "Up-regulation of the cytokine is also evident in sections of colon adenoma, raising the possibility that dysregulation of FSTL1 production occurs at early stages of colon carcinogenesis." (PMID 30131854, 2018).
congenital malformations (1 paper, 2012). "Anyway, Fstl1 mutant mice provide a good model to study the mechanisms of the interaction between SHH and BMP signaling pathways to regulate cell proliferation and differentiation during ureter development and in congenital malformations of the urinary tract." (PMID 22485132, 2012).
cutaneous squamous cell carcinoma (1 paper, 2024). "THOC7-AS1 and FSTL1 expression are frequently upregulated in cutaneous squamous cell carcinoma (cSCC)." (PMID 38605354, 2024). "In our investigation, we unveiled the oncogenic role of FSTL1 in cutaneous squamous cell carcinoma." (PMID 38605354, 2024). "In summary, these preliminary findings collectively suggest an oncogenic role for FSTL1 in cSCC, supported by its elevated expression in both clinical samples and cell lines, indicating its potential significance in the context of cutaneous squamous cell carcinoma." (PMID 38605354, 2024).
depression (1 paper, 2024). "Of thirteen depression‐associated DRPs, seven proteins including DDC, FGFR2, KIBRA, MED22, OLIG1, RAI1, SLIT2 were upregulated, whereas six proteins including COX3, CRHBP, CSMD1, FSTL1, GRIK4, and LMTK3 were downregulated." (PMID 39373701, 2024). "By contrast, the upregulation of DDC, FGFR2, KIBRA, and MED22, and the downregulation of FSTL1, GRIK4, and LMTK3 in the RagA transgenic mice were negatively correlated with depression." (PMID 39373701, 2024).
End Stage Liver Disease (1 paper, 2025). Final stage of a liver disease when the liver failure is irreversible and LIVER TRANSPLANTATION is needed. "Correlation analyses revealed that the baseline serum level of FSTL1 was positively correlated with improvements in the model for end-stage liver disease (MELD) score (R = 0.45)." (PMID 40050288, 2025).
endometrial tumors (1 paper, 2019). "Moreover, Fstl1 has also been identified as a tumor suppressor in ovarian and endometrial tumors partially through inhibition of cell proliferation, migration, and invasion." (PMID 30635025, 2019).
graft versus host disease (1 paper, 2022). An immune system disorder that occurs after allogeneic hematopoietic stem cell transplant and is a reaction of donor immune cells against host tissues. "In this study, we investigated the perioperative course of a cytokine that has been related to graft-versus-host disease named Follistatin-like 1 and cytokines associated with neutrophil activation." (PMID 36290379, 2022).
heart injury (1 paper, 2019). Injury to the heart. "Follistatin-like 1 (Fstl1) is documented as a novel pro-survival cardiokine for cardiomyocytes, and it is protective during ischemic heart injury." (PMID 30635025, 2019).
Hydrocephalus (1 paper, 2026). Hydrocephalus is an active distension of the ventricular system of the brain resulting from inadequate passage of CSF from its point of production within the cerebral ventricles to its point of absorption into the systemic circulation. "CAPS and FSTL1 may represent exploratory proteins of interest within different hydrocephalus-related annotation contexts." (PMID 42293101, 2026).
hydronephrosis (1 paper, 2012). Collection of urine in the renal pelvis that results in dilatation of the renal pelvis and calyces. "However, from these histological results, we found that Fstl1 mutant kidney was reduced in size and displayed the dilatation of the pelvis and atrophy of papilla at E17.5, suggesting Fstl1-/- kidneys exhibited hydronephrosis at this stage (Figure." (PMID 22485132, 2012).
hyperparathyroidism (1 paper, 2024). Hyperfunction of the parathyroid glands resulting in the overproduction of parathyroid hormone. "Five drug targets (CMKLR1, FSTL1, IGSF11, PIK3C3 and SLC40A1) showed significant causation with hyperparathyroidism in both eQTLGen and GTEx cohorts by MR analysis." (PMID 38499600, 2024).
Immunodeficiency (1 paper, 2021). Failure of the immune system to protect the body adequately from infection, due to the absence or insufficiency of some component process or substance. "Therefore, FSTL1 deficiency in mTEC cells decreased the proliferation of DN thymocytes and production of T cells, which could result in immunodeficiency and impairment of adaptive immunity." (PMID 33639614, 2021).
interstitial lung disease (1 paper, 2025). A diverse group of lung diseases that affect the lung parenchyma. "We have identified FSTL1 as a novel profibrotic factor for those fibrotic interstitial lung disease (ILD) 20-22." (PMID 39990230, 2025).
keloid (1 paper, 2025). An irregularly shaped, elevated mark on the skin caused by deposits of excessive amounts of collagen during wound healing. "In agreement with our interactome, regulation of ELN, COL5A2, FSTL1 and COL1A1 was demonstrated experimentally using a miR-29b mimic and antagomir in primary human skin fibroblasts and other models in the context of treatment of keloid formation and fibroplasia using miR-29b mimic Remlarsen." (PMID 39883689, 2025).
kidney injury (1 paper, 2021). Trauma to the kidney. "Adams and coworkers studied the role of FSTL1 in acute kidney injury secondary to cisplatin and they suggested that FSTL1 was protective." (PMID 34502419, 2021).
malnutrition (1 paper, 2025). Inadequate nutrition resulting from poor diet, malabsorption, or abnormal nutrient distribution. "By influencing myostatin, FSTL-1 plays a crucial role in muscle growth and maintenance, especially under conditions of energy deficiency or malnutrition." (PMID 40077702, 2025).
metastatic cancer (1 paper, 2023). A carcinoma which has spread from the original site of growth to another anatomic site. "However, metastatic cancer in the lungs increased remarkably in the FSTL1-deficient mice." (PMID 37238210, 2023).
metastatic prostate carcinoma (1 paper, 2023). A carcinoma that arises from the prostate gland and has spread to other anatomic sites. "Unlike ligands, soluble antagonists in metastatic prostate cancer patients are consistently increased in patients with CHRD at 12%, NOGGIN, SOSTDC1, FSTL1 at 7% and GREM2 at 6% of patients." (PMID 36054271, 2023).
mitral valve prolapse (1 paper, 2019). A fairly common and often benign valvular heart disorder characterized by redundancy or hooding of mitral valve leaflets so that they prolapse into the left atrium, often causing mitral regurgitation. "It should be noted, that in different genomewide association studies (GWAS), FSTL1 has never been associated with mitral valve prolapse." (PMID 30722102, 2019).
osteonecrosis (1 paper, 2025). A none disease characterized by death of bone tissue due to a lack of blood supply. "In osteonecrosis, elevated FSTL1 promotes NF-κB-dependent cytokine release and tissue degradation, while in infections and chondrocytes, it drives inflammation via TLR4/NF-κB and MMP induction." (PMID 40808692, 2025).
osteosarcoma (1 paper, 2024). A usually aggressive malignant bone-forming mesenchymal neoplasm, predominantly affecting adolescents and young adults. "Currently, certain pharmaceutical companies are exploring the role of the FSTL1-targeting drug PFI-103 in preclinical trials for osteosarcoma and solid tumors." (PMID 38605354, 2024). "Additionally, FSTL1 knockdown in osteosarcoma inhibits proliferation, invasion, spheroid formation, and ALCAM expression, while anti-FSTL1 treatment restores NK cell activity, killing tumor cells and inhibiting osteosarcoma growth and metastasis." (PMID 38605354, 2024). "Notably, the pharmaceutical company has registered the FSTL1-targeting drug PFI-103, exploring its role in osteosarcoma and solid tumors, providing a strong reference for further research." (PMID 38605354, 2024).
postmenopausal osteoporosis (1 paper, 2026). Metabolic disorder associated with fractures of the femoral neck, vertebrae, and distal forearm. "This study systematically delineates the expression dynamics of follistatin-like protein 1 (FSTL1) in postmenopausal osteoporosis (PMOP) and elucidates its role in skeletal homeostasis." (PMID 41943821, 2026).
renal dysfunction (1 paper, 2019). "In this study, plasma FSTL1 was significantly associated with CCr and hsCRP in patients with CAD, but plasma FSTL1 in patients with and without MACCE were not significantly different when patients with renal dysfunction and/or high-grade systemic inflammation were included." (PMID 31034503, 2019).
Right ventricular hypertrophy (1 paper, 2017). In this case the right ventricle is more muscular than normal, causing a characteristic boot-shaped (coeur-en-sabot) appearance as seen on anterior- posterior chest x-rays. "Haploinsufficiency of Fstl1 in mice contributed to an exacerbated HPH, as demonstrated by increased right ventricular systolic pressure, pulmonary arterial muscularization and right ventricular hypertrophy index." (PMID 28361925, 2017).
sarcopenia (1 paper, 2024). Progressive decline in muscle mass due to aging which results in decreased functional capacity of muscles. "DCN, FSTL1, and COL12A1 are new candidate biomarkers for the comorbidity of SCI and sarcopenia." (PMID 39281413, 2024).
schizophrenia (1 paper, 2018). A major psychotic disorder characterized by abnormalities in the perception or expression of reality. "Recently, a SNP in miR-198, whose expression is mutually exclusive to Fstl1, was found to be associated with schizophrenia." (PMID 30348171, 2018). "We found that the expression of Ifitm3 increased the extracellular level of Fstl1, while other studies reported the increased expression of Ifitm3 in the brains of schizophrenia patients." (PMID 30348171, 2018).
scleroderma (1 paper, 2022). Scleroderma is a rare autoimmune connective tissue disorder characterized by abnormal hardening of the skin and, sometimes, other organs. "Besides, deficiency of HDAC5 in endothelial cells of patients with Scleroderma increases FSTL1 expression and improves the ability of endothelial cells to form tubules in Matrigel, suggesting that FSTL1-mediated promotion of angiogenesis is dependent on HDAC5." (PMID 36091401, 2022).
scoliosis (1 paper, 2017). A congenital or acquired spinal deformity characterized by lateral curvature of the spine. "ELISA results showed that the serum FSTL1 levels in the protrusion group (7.240±0.905 ng/mL) and the extrusion group (11.080±1.961 ng/mL) were significantly higher than that of the scoliosis controls (5.301±0.779 ng/mL)." (PMID 28498809, 2017). "In this study, enzyme-linked immune sorbent assay (ELISA) and western blots were used to investigate FSTL1 expression in LDH patient samples and scoliosis patient samples (controls)." (PMID 28498809, 2017).
seronegative spondyloarthropathy (1 paper, 2011). "However, serum FSTL1 levels were not elevated in seronegative spondyloarthropathy, including AS, PsA and ReA, possibly because of less frequent autoantibody-mediated vascular injury and vasculitis." (PMID 21303509, 2011).
skin squamous cell carcinoma (1 paper, 2025). A carcinoma arising from the squamous cells of the epidermis. "Notably, FSTL1 has been shown to induce EMT in skin squamous cell carcinoma by interacting with Zinc finger E-box binding homeobox 1 (ZEB1), enhancing tumor cell proliferation, migration, and invasion." (PMID 40808692, 2025).
skin tumors (1 paper, 2024). "To explore this, we analyzed the correlation between FSTL1 and the EMT marker ZEB1 expression in various squamous cancers, skin tumors, and sun-exposed/unexposed skin using data from TCGA and GTEx." (PMID 38605354, 2024).
stomach adenocarcinoma (1 paper, 2020). "As FSTL1 expression increased, most immune-related pathways were activated in GC, CYTOKINE_CYTOKINE_RECEPTOR_INTERACTION, INNATE_IMMUNE_SYSTEM, NATURAL_KILLER_CELL_MEDIATED_CYTOTOXICITY, and others in stomach adenocarcinoma (STAD)." (PMID 33292276, 2020).
Streptococcus pneumoniae infection (1 paper, 2023). "Moreover, FSTL1 was expressed after Streptococcus pneumoniae infection, positively modulated the NLRP3 (NACHT, LRR, and PYD domain-containing protein 3) inflammasome, and promoted inflammatory injury during infection through the TLR4/NF-κB signaling pathway." (PMID 37322475, 2023).
synovitis (1 paper, 2011). Inflammation of a synovial membrane. "It is possible that female OA patients suffered from more severe synovitis and joint damage, and therefore produced more secreted FSTL1 than the male OA patients." (PMID 22117761, 2011).
systolic heart failure (1 paper, 2016). Heart failure caused by abnormal myocardial contraction during systole leading to defective cardiac emptying. "Furthermore, increased expression of Fstl1 is observed in cardiomyocytes and endothelial cells in human systolic heart failure." (PMID 27145224, 2016).